HK2 (hexokinase 2)
Diseases named in the same sentence as HK2 in open-access papers (continued):
Sharing a sentence is not in itself a finding about the gene and the disease.
cancer (continued). "It covalently binds to the glycolytic enzymes; hexokinase-2, Glyceraldehyde-3-phosphate dehydrogenase and mitochondrial; succinate dehydrogenase, in addition, to the endoplasmic reticulum and the lysosomes resulting in severe depletion in ATP and cancer death." (PMID 26526196, 2015). "If true, combining HK2 inhibitors with oncolytic viruses could inadvertently limit their therapeutic utility for the treatment of cancer." (PMID 26247723, 2015). "Several glycolytic inhibitors that target HK2 have been proposed in cancer treatment." (PMID 25010005, 2014). "Also the well-established hypoxia-responsive gene HK2, which phosphorylates glucose and thus contributes to the glycolytic flux in cancer cells, was significantly up-regulated by hypoxia in the fragments, both in the microarray analysis and by qPCR." (PMID 24460801, 2014). "In addition to its critical metabolic role, HK2 can also promote cancer by repressing mitochondrial function on cell death, immortalizing cancer cells." (PMID 23431283, 2013). "In the present study, we found that the over-expression of the three glycolysis associated genes, GLUT1, HK1, and HK2, was not consistently seen in the NETs, which confirms the lower glucose utilization of NETs compared to several other cancer entities." (PMID 26824929, 2013). "Likewise, HK2 is upregulated in cancer cells and plays a key role in regulating the Warburg effect in GBMs." (PMID 24213470, 2012). "Likewise, miR-143 has also been identified as an essential regulator of cancer glycolysis via targeting HK2 in human lung cancer." (PMID 23164426, 2012). "Expression of HK2 has been indicated in rapidly growing cancer cells." (PMID 19284555, 2009). "The p values for the hypothesis that addition of free PSA, intact PSA and hK2 improved predictive accuracy (that is, increased the AUC) for detecting high-grade cancer were 0.04 and 0.16 for the laboratory and clinical models, respectively." (PMID 18611265, 2008). "Therefore, HK2 represents a promising target for cancer therapy." (PMID 39991762, 2025). "Furthermore, differences were observed in the expression of several non-canonical and/or embryonic isoforms (HK3, HKDC1, ALDA, GADPH-S, PGK2, and PKM) between patients and controls, as well as in the expression of isoforms considered hallmarks of cancer, such as HK2." (PMID 41009047, 2025). "HK2, the first key rate-limiting enzyme of the “Warburg effect”, catalyzes the conversion of glucose to G-6-P, which is highly expressed in OC tissues and correlates directly with advanced and high-grade cancers and plays a role as an independent prognostic factor." (PMID 40045411, 2025). "Moreover, hexokinase 2 (HK2), a rate-limiting enzyme in glycolysis, a transcriptional target of STAT3 and crucial for the Warburg effect, contributing to altered glucose metabolism in cancer cells, has been implicated in tamoxifen resistance." (PMID 39859445, 2025). "Furthermore, HK2 has demonstrated its significance in a broad spectrum of cancer types." (PMID 38383348, 2024). "Notably, HK2 expression is significantly higher in cancer cells than in normal cells, correlating with accelerated proliferation and enhanced resistance to drugs through metabolic reprogramming across various cancer types." (PMID 38750462, 2024). "The high expression of HK2 has been identified as an independent risk factor for RCC; It also shows a positive correlation with immune cell infiltration and prognosis in kidney cancer patients, playing an important role in the occurrence and development of cancer." (PMID 37347113, 2023). "Similarly, HK2 regulates cancer cell apoptosis by interacting with the AKT signaling pathway." (PMID 37542027, 2023). "Moreover, different cancer-overexpressed non-coding RNAs also promote HK2 mRNA stability, with circCDKN2B-AS1 complexing with IGF2BP3 and HK2 mRNA to sustain aerobic glycolysis, while the related IGF2BP2 protein also increases HK2 mRNA stability through forming a complex with the lncRNA CASC9." (PMID 37059726, 2023).
cancer (continued). "Elevated glucose metabolism, hypoxia-induced GLUT, LDH-A, and PFKFB3 overexpression, and the AKT- and c-Myc-mediated transcriptional activation of HK2 are observed in most cancer cells, and these metabolic changes may be exploited for developing effective therapeutic approaches." (PMID 36768924, 2023). "In this regard, studying the modulatory effects of miRNAs and lncRNAs on those glycolytic proteins linked with cancer progression, e.g., HK1, GAPDH, PKM2, GLUT1, GLUT3, HIF-1α, CAV1, Ras, HK2, LDHA, PGI/AMF, and PFKFB3, might be very favorable for the design of novel treatments for PC." (PMID 36332600, 2023). "Therefore, HK2 is believed to be an ideal cancer-specific target for HCC therapy." (PMID 36192599, 2022). "In addition to satisfying energy requirements, HK2 expression protects cancer cells from apoptosis by binding to Voltage Dependent Anion Channel 1 on the outer mitochondrial membrane and by limiting reactive oxygen species (ROS) production in mitochondria by maintaining local ADP levels." (PMID 35269760, 2022). "Thus, targeting LDH-A or HK2 in cancers that are highly glycolytic and overexpress these proteins may be beneficial." (PMID 36358687, 2022). "Therefore, the high HK activity in cancer cells mainly results from the induced expression of HK2." (PMID 36230492, 2022). "Importantly, as we had previously suggested the feedback inhibition of HK2 by its own catalytic product G6P could be used as a strategy to target HK2 for cancer therapy by developing mimetics of G6P or 2DG6P to inhibit its activity." (PMID 35173161, 2022). "Besides, the Warburg effect of cancers could be accelerated by WTAP through m6A-dependent regulation of hexokinase 2 (HK2) stability." (PMID 36171885, 2022). "Moreover, HK2 depletion was shown to promote cancer cell death and stimulated oxidative phosphorylation, revealing the importance of enhanced HK2 expression and indicating blocking HK2 may have important therapeutic impact for patients with HCC." (PMID 36712976, 2022). "However, the selectivity of MJ to HK2 in cancers is relatively poor." (PMID 36230492, 2022). "Similarly, HK2 expression is upregulated in a wide range of cancer types." (PMID 35805008, 2022). "Moreover, upregulation of HK2 drives glucose metabolism and promotes sufficient number of metabolic intermediates to support anabolic processes (such as nucleic acid, lipid and protein synthesis), which is characteristic of rapidly dividing cancer cells." (PMID 35659359, 2022). "In addition, miRNAs regulate the expression of HK2 in cancer cells." (PMID 33922649, 2021). "To explore whether SUMOylation of HK2 modulated the cancer cell aggressive phenotype, we performed proliferation curve analysis, BrdU incorporation, and anchorage-independent colony-formation assays to test cell proliferative activity and oncogenesis with different HK2 mutations." (PMID 33753739, 2021). "Besides acting as a downstream factor of HIF1, C-MYC has a synergistic effect with HIF-1 on inducing glycolysis by promoting 3-phosphoinositide dependent kinase-1 and HK2 and inducing angiogenesis, leading to hypoxia adaptation, internal environment stability, and chemoresistance in cancer." (PMID 34540667, 2021). "However, the downregulation of HK2 activity in cancers could prevent the aerobic glycolysis mechanism, leading to a reduction in tumor growth." (PMID 34771718, 2021). "Because more prominent expression of hexokinase 2 was observed in adipocytes at the invasive front of cancer than those at the distant site, this reprogramming of glucose metabolism in adipocytes could increase the FDG uptake heterogeneity and intensity in peritumoral breast AT." (PMID 34683170, 2021). "Thus, we postulate these residues serve as a regulatory site for HK2 and may provide new directions for the design of anticancer therapeutics that reduce the rate of glycolysis in cancer through specific inhibition of HK2." (PMID 33187984, 2021).
cancer (continued). "Therefore, targeting hexokinase-2 will block glucose metabolism in cancer cells, which may inhibit its proliferation with minimum side effects reported." (PMID 32874134, 2020). "Therefore, HK2 has been proposed as a therapeutic target for cancers." (PMID 33520999, 2020). "On the other hand, high p62 expression induces high hexokinase 2 and hypoxia-inducible factor α expression via the upregulation of mTORC1 and NF-κB activity and the inhibition of von Hippel–Lindau E3 ubiquitin ligase activity, leading to enhancement of glycolysis in cancer." (PMID 31708690, 2019). "Indeed, the regulation of HK2 is complicated in cancer cells." (PMID 31137633, 2019). "Indeed, HectH9 knockdown sensitized cancer cell response to doxorubicin and paclitaxel in various cancer cells, highlighting that targeting HectH9/HK2 axis could be a new approach for restoring cancer cells’ susceptibility to currently used chemotherapy." (PMID 31201299, 2019). "Cancer-induced mutations and alterations of signaling pathways activate PI3K-Akt, which promotes transcriptional induction of glucose transporters [e.g., glucose transporter 1 (GLUT1)], activation of glycolytic enzymes (e.g., HK2, PFKFB3), and parallel activation of mTOR." (PMID 30123774, 2018). "Thus for some cancers targeting HK2 with inhibitory drugs is an objective." (PMID 29352298, 2018). "However, HK2 expression is markedly elevated in cancer cells." (PMID 29687779, 2018). "However, future studies are necessary to further investigate the role HK2 inhibition could play in cancer therapy." (PMID 30140438, 2018). "However, like HK1+ cells/tissues, HK1+HK2+ cancers are not susceptible to this therapy, despite the reduction in their HK2-driven glycolytic activity." (PMID 29988332, 2018). "Therefore, finding new HK2-targeting candidates is urgent for cancer treatment." (PMID 28427443, 2017). "So it seemed feasible that HK2 could be a selective therapeutic target for cancer." (PMID 25053988, 2014). "HK2, the predominant isoform overexpressed in malignant tumors, strategically binds to the outer mitochondrial membrane coupling ATP formation in mitochondria to the phosphorylation of glucose, thus conferring cancer cells with a highly glycolytic phenotype and ample biosynthetic precursor." (PMID 23431283, 2013). "Moreover, everolimus inhibited cellular glycolysis in Panc-1 cells in a time-dependent manner, which may partly be explained by the upregulation of miR-143 and the deregulation of HK2, the latter of which plays an essential role in glycolysis in cancer cells." (PMID 23251295, 2013). "We chose to focus on HK2 as a potential target of miR-143 for further functional analysis, because we hypothesized that miR-143 mediated regulation of HK2 may account for the changes in glucose metabolism observed in many cancer cells." (PMID 22691140, 2012). "c-Myc expression in cancer cells increases LDH, GLUT1, HK2, and alters transcriptional programming in transformed cells to be more similar to embryonic cells, which is a dedifferentiated, hyperplastic and hyper-prolific state." (PMID 41586225, 2025). "Cross-cancer comparative analyses further indicate that HCC TANs show unique metabolic programming, characterised by upregulation of glycolytic genes (HK2, PFKP) and fatty acid oxidation genes (carnitine palmitoyltransferase 1A[CPT1A])." (PMID 41451221, 2025). "Through a comparative analysis, we identify consistent upregulation of glycolytic enzymes such as LDHA, PKM2, and HK2, as well as nutrient transporters like GLUT1, ASCT2, and LAT1, which contribute to cancer progression, metastasis, and therapy resistance." (PMID 41154605, 2025). "In CRC, HK2 inhibition diminishes the epithelial-to-mesenchymal transition (EMT), which plays a defining role in cancer metastasis." (PMID 40076506, 2025). "Benitrobenrazide is a nanomolar inhibitor of HK2 (IC50 of 0.53 ± 0.13 μM), induces apoptosis and inhibits proliferation of HK2-overexpressed cancer cells." (PMID 40941984, 2025).
cancer (continued). "The upregulation of glycolysis through HIF1α target genes (such as HK2, GLUT1, PDK1, and LDHA) provides cancer cells with rapid ATP production and biosynthetic intermediates." (PMID 39807625, 2025). "Cancer cells upregulate glucose transporters (GLUT1/3) and glycolytic enzymes (e.g., HK2, LDHA) to fuel rapid proliferation, outcompeting immune cells for glucose in the nutrient-scarce TME." (PMID 40734168, 2025). "Several proteins involved in glycolysis, including glucose transporter 1 (GLUT1), hexokinase 2 (HK2), and lactate dehydrogenase A (LDHA), are overexpressed in cancers." (PMID 41392241, 2025). "Essential targets in therapeutic targeting of cancer metabolism are glycolytic enzymes, including LDHA, PKM2, HK2, ALDOA, G6PD, PPP cycle, glutamine serine metabolism and pyruvate oxidation." (PMID 40076506, 2025). "The authors observed that in cancer tissue samples, overexpressing MAO-A the glycolysis-stimulating effect was in conjunction with the high expression of HK2 and the low expression of pyruvate dehydrogenase (PDH)." (PMID 39714760, 2025). "miR‐5586‐5p also suppresses the expression of glycolytic genes, lactate dehydrogenase A (LDHA), hexokinase 2 (HK2), phosphoglycerate kinase 1 (PGK1), and solute carrier family 2 member 1 (SLC2A1), thereby suppressing glycolysis and cancer progression." (PMID 40448344, 2025). "STAT3 plays a crucial role in advanced cancers by promoting glycolysis through the transcriptional activation of HIF-1α and HK2 in vitro." (PMID 39859445, 2025). "By upregulating molecules involved in glycolysis, such as GLUT1, LDHA and HK2, HIF‐1α enhances glucose uptake and lactate production, providing cancer cells with energy and biosynthetic precursors essential for rapid growth and survival." (PMID 39993964, 2025). "We demonstrate that the HK2 glucose kinase is a bona-fide RBP that regulates the translation of the SOX10 mRNA, thereby regulating cancer-relevant phenotypes." (PMID 40956859, 2025). "For instance, buparlisib suppresses the expression of hexokinase 2 (HK2) and pyruvate kinase M2 (PKM2), critical glycolytic enzymes, thereby hindering glycolytic flux and energy production in cancer cells." (PMID 39953539, 2025). "Invaluable previous work has shown that in a PI3K/Akt pathway-dependent manner, HK2 is overexpressed and PDH is downregulated in cancer cells, thus supporting the Warburg effect." (PMID 39714760, 2025). "NSD2-induced H3K36me2 also upregulates key enzymes in glucose metabolism, including hexokinase 2 (HK2) and glucose-6-phosphoate dehydrogenase (G6PD), in endocrine therapy-resistant cancer cells." (PMID 41301842, 2025). "Key glycolytic enzymes such as HK2 and PKM2 are overexpressed in NSCLC and are critical for maintaining the high glycolytic flux observed in cancer cells." (PMID 40469185, 2025). "To demonstrate that the RNA-binding activity of HK2 sustains its ability to regulate mRNA translation, we focused our study on one given mRNA (SOX10) that is also highly relevant in cancer." (PMID 40956859, 2025). "This study uncovers a novel mechanism for FBZ’s antitumor effects and highlights HK2 as a critical link between metabolism and cell death, suggesting FBZ as a potential candidate for cancer therapy." (PMID 40756987, 2025). "HIF-1 plays a fundamental role in the adaptation of cancer cells to hypoxia by activating genes involved in aerobic glycolysis, such as glucose transporter (GLUT), hexokinase 2 (HK2), and VEGFA." (PMID 40003897, 2025). "Bergenin demonstrated a suppressive impact on the development of cancer cells, decelerated the metabolic process of glycolysis, and induced intrinsic apoptosis in OSCC via lowering the expression of HK2." (PMID 39834829, 2024). "This study investigates the anticancer effects and mechanisms of TCS in combination with benserazide (Benz), a HK2 inhibitor, in Hela and SCC25 cancer models." (PMID 39713255, 2024).
cancer (continued). "Inhibitors of HK2, such as 2‐deoxyglucose (2‐DG) and PKM2 inhibitors can disrupt the glycolytic flux, impairing energy production and biosynthesis in cancer cells." (PMID 39601114, 2024). "Moreover, the genetic ablation of hexokinase 2 (HK2), a key regulator during glucose metabolism linked to malignant growth in many types of cancers, also reduced metastasis, suggesting that TQ’s anti-metastatic properties may be linked to its ability to modulate glucose metabolism." (PMID 39769996, 2024). "In recent years, benitrobenrazide and benserazide containing imine moiety have been synthesized and characterized as promising inhibitors of hexokinase 2 (HK2), an enzyme overexpressed in most cancer cells." (PMID 38338374, 2024). "The β-catenin-mediated activation of glycolytic proteins promotes the oncogenic potential of c-Myc, since c-Myc upregulates the band level of HK2, LDHA, and PKM2 in cancer cells." (PMID 39273365, 2024). "To further assess the role of intracellular fructose production in oncogenic glycolysis, we generated cancer cells with impaired glucose metabolism by deleting both HK1 and HK2." (PMID 39406918, 2024). "In general, AuNPsp-PEG and AuNPr-PEG tend to increase the expression of enzymes involved in glycolysis, such as HK2 and PKM in PC3 and LNCaP cells, suggesting they play a role in supporting cancer cell survival." (PMID 36899923, 2023). "Many metabolic enzymes have been studied as targets for cancer treatment, such as GLUT1 inhibitor STF-31, HK2 inhibitor phenylnitrobenzylhydrazine, LDHA inhibitor NCI-006D, etc 20-22." (PMID 37670970, 2023). "Metformin inhibits glycolysis rate limiting enzyme of glycolysis, hexokinase 2 (HK2), and mitochondrial respiratory complex 1, which result in the reduction of mitochondrial ATP production in cancer cells." (PMID 36614197, 2023). "Thus, HOTAIR may promote cancer cell energy metabolism by upregulating HK2 expression." (PMID 37189687, 2023). "We further investigated the effects of the interplay and the underlying mechanisms between circ‐CTNNB1 and RBM15 on the regulation of target genes (GPI, HK2 and PGK1) and cancer progression in OS cells." (PMID 36181462, 2023). "CXCL1 increases cancer cell proliferation and increases glycolytic enzyme expressions, such as glucose transporter 1 (GLUT1), hexokinase 2 (HK2), and lactate dehydrogenase A (LDHA)." (PMID 37408240, 2023). "Cancer cells containing mutant BRCA1 were also determined to suppress glycolysis by repressing the genes GLUT1, HK1, HK2, and LDHA." (PMID 37110218, 2023). "PGC1α upregulates hexokinase 2 (HK2) and GLUT4 in cancer cells, but the principal PGC1α targets are mitochondrial biogenesis and OXPHOS genes in cancer cells." (PMID 37762231, 2023). "The observation that most normal cells express HK1 while cancer cells express HK1 and HK2 stimulated interest in reducing HK2 activity in cancers." (PMID 37109475, 2023). "c-Myc is the upstream positive regulator of the Prox1-inhibited genes (GLUT1, HK2, and PDK1), identified here, as well as the Warburg effect in cancer cells." (PMID 37508533, 2023). "Studies have found that abnormal expression of MYC exists in cancer, and the expression of MYC is closely related to genes regulating glucose metabolism, such as GLUT1, HK2, PFKM, etc.." (PMID 37663261, 2023). "The miR-143 high expression downregulates the downstream key molecules of the mTOR signaling pathway including HK2 and KRAS, thus influencing cancer cells metabolism reprogramming." (PMID 37208722, 2023). "In line with reported effects of arginine on glycolysis in cancers, we observed increased expression of glucose transporter 3 (GLUT3) and hexokinase 2 (HK2) in ARG1/AGMAT-expressing cells." (PMID 37804830, 2023). "By targeting hexokinase HK2, hypoxia-down-regulated miR-125a controlled HCC glycolysis and tumorigenesis, adding a novel aspect to hypoxia-mediated modulation of cancer metabolism." (PMID 36483029, 2022).